LINC01795 (long independently transcribed non-coding RNA 1795)
Gene: Long non-coding RNA gene on chromosome 2 (58,275,532 to 58,297,857, forward strand). Ensembl gene ENSG00000225226.
Diseases named in the same sentence as LINC01795 in open-access papers:
LINC01795 is named in the same sentence as 1 disease in open-access papers, as found by Europe PMC text mining. Sharing a sentence is not in itself a finding about the gene and the disease.
LINC01795 shares sentences with these, for which no sentence is quoted: schizophrenia (1 paper).